BAX (BCL2 associated X, apoptosis regulator)
Diseases named in the same sentence as BAX in open-access papers (continued):
Sharing a sentence is not in itself a finding about the gene and the disease.
gastric cancer (41 papers, 1999 to 2026). A primary or metastatic malignant neoplasm involving the stomach. "Despite these constraints, the insights gained from this research lay a solid groundwork for future investigations into the BAX gene and its involvement in the molecular pathways underlying peptic ulcer disease and gastric cancer." (PMID 41614769, 2025). "Elevated BAX expression, however, is associated with gastric cancer onset and could be a promising prognostic indicator." (PMID 41614769, 2025). "In conclusion, the results of this exploratory study indicate that the presence of the AA SNP G-248A BAX genotype may be a significant risk factor for the development of gastric cancer, and its overexpression may be a positive prognostic marker in GC." (PMID 41614769, 2025). "The relative BAX gene expression with regard to SNP G-248A individual genotypes was estimated in the gastric cancer group." (PMID 41614769, 2025). "This is different from the pattern mentioned in the introduction that TRIM17 promotes cell survival by degrading BAX in gastric cancer." (PMID 41145484, 2025). "This is particularly relevant for the case of gastric cancer, where our in silico studies showed that higher levels of BAX gene expression occurred in cancer tissue, and increased mRNA was a positive prognostic factor." (PMID 41614769, 2025). "This study underlines the complex correlation between genetic factors and disease, highlighting the potential of the BAX gene as a biomarker for gastric cancer prognosis and therapeutic targeting." (PMID 41614769, 2025). "In silico studies using the TCGA-STAD (The Cancer Genome Atlas Stomach Adenocarcinoma) data form the UALCAN database showed upregulated expression of the BAX gene in gastric cancer tissue compared to normal tissue (p < 0.001)." (PMID 41614769, 2025). "This work also demonstrated that TRIM17 is transcriptionally upregulated in gastric cancer patients, while BAX expression is inversely related to TRIM17 in those cohorts." (PMID 39851497, 2025).
gastric cancer (continued). "Another study shows that TRIM17, through interaction with BAX, which results in its proteasomal degradation, led to the inhibition of apoptosis and excessive cell proliferation in the gastric cancer cell lines AGS and HGC-27." (PMID 41614769, 2025). "The relative expression level of the BAX gene in samples from patients, 36 with peptic ulcer, 13 with gastric cancer, and 6 tissues collected beyond the margin of cancer tissue and macroscopically considered as healthy, were successfully analyzed." (PMID 41614769, 2025). "On the other hand, TRIM17 has been shown to promote the proliferation of gastric cancer cells via ubiquitination-mediated proteasomal degradation of apoptotic protein BAX." (PMID 39851497, 2025). "Further, in silico analyses demonstrated elevated BAX expression in gastric cancer tissues, correlating with advanced histological grades and improved overall survival rates." (PMID 41614769, 2025). "In BGC-823 gastric cancer cells, caspase-3, -9, and cytochrome c increased, the ratio of BAX to Bcl-2 increased, and apoptosis was induced through the inhibition of the MAPK and PI3K signaling pathways." (PMID 36142874, 2022). "Along with the diverse molecular functions enriched for MSI events in these tumor types, some genes (TGFBR2, ACVR2A, and BAX) are particularly susceptible in MSI-H CRCs, and BAX is also susceptible in MSI-H gastric cancers." (PMID 36531239, 2022). "Upregulation of BAX and down-regulation of Bcl-2 by Res are involved in these anti-tumor impacts in implanted human primary gastric carcinoma cells in nude mice." (PMID 33478512, 2021). "Earlier reports suggested that apoptotic genes like APAF-1, Bcl-2, BAX, and Bcl-2 family were found to be up-regulated in gastric cancer tissues." (PMID 32993565, 2020). "Overexpression of PLOD2 upregulated the expression of BCRP protein and inhibited apoptosis by decreasing BAX and increasing the level of Bcl2, enhancing the resistance of gastric cancer cells to 5-FU." (PMID 32284742, 2020). "Similar studies in glioblastoma, cervical and gastric cancer confirm the role of Rab31 in regulating apoptosis with overexpression of Rab31 correlated with decreased expression of BAX, cleaved caspase 3 and PARP, concomitant with increased expression of BCL-2." (PMID 31973201, 2020).
gastric cancer (continued). "Rab14 silencing drives apoptosis in SGC-7901 and BGC-823 gastric cancer lines and this is associated with reduced AKT activation and cell proliferation and increased expression of BAX apoptotic proteins." (PMID 31973201, 2020). "Additionally, TRIM17 interacts with BAX and promotes its ubiquitination and proteasomal degradation, thereby inhibiting BAX-dependent apoptosis in both the absence and presence of apoptotic stimuli in gastric cancer cells." (PMID 40819060, 2025). "In the group of patients with gastric cancer, BAX gene expression level was variable." (PMID 41614769, 2025). "This regulatory pattern is different from the mechanism by which TRIM17 inhibits apoptosis by degrading BAX in gastric cancer, suggesting that TRIM17 may exert a pro-cancer effect by targeting specific substrates in different tumors." (PMID 41145484, 2025). "The findings of our study indicate a potential association between the AA genotype of the G-248A polymorphism in the BAX gene and an increased risk for gastric cancer, whereas this genetic variant does not seem to affect peptic ulcer disease susceptibility." (PMID 41614769, 2025). "The extracts from P. vulgaris inhibited the proliferation of gastric cancer cells by increasing the levels of BAX and decreasing Bcl-2 levels and suppressed the proliferation of gastric carcinoma by downregulating vascular endothelial growth factor (VEGF) expression." (PMID 38675663, 2024). "Interestingly, it has been reported that CRAPB2 accelerates ubiquitination-mediated BAX degradation in gastric cancer cells, thereby alleviating mitochondrial apoptosis and promoting oxaliplatin resistance." (PMID 38195606, 2024). "Moreover, in gastric cancer cells, eupatilin induces apoptosis by regulating apoptotic proteins such as BAX and BCL2 and inducing mitochondrial depolarization." (PMID 34203665, 2021). "Moreover, ginsenoside-Rh2 inhibited proliferation of SGC-7901 side population gastric cancer cells by the induction of cell cycle arrest, as well as cell apoptosis, and altered BAX/Bcl-2 protein expression." (PMID 34572730, 2021). "Furthermore, overexpression of ING3 in gastric cancer cells resulted in apoptosis with increased BAX and CASPASE-3 expression and down-regulated expression of the anti-apoptotic protein BCL2." (PMID 31905726, 2019). "The anti-gastric cancer activity of anti-MUC1 and rosmarinic acid is reflected in the inhibition of mRNA expression of enzymes that produce cancer-associated antigens and specific antigens; the promotion of BAX, Bad and Caspase-3 and -9; and inhibition of Bcl-2 expression." (PMID 38675663, 2024). "Lastly, BAX showed positive correlations with several immune inhibitors, including PDCD1 and TIGIT in gastric cancer." (PMID 40652278, 2025).
gastric cancer (continued). "Indeed, the BAX protein has been found to be less prevalent in esophageal squamous cell carcinoma tissue with the AA G-248A SNP compared to GG; hence, the present study compares the BAX G-248A genotypes between patients with gastric cancer and healthy individuals." (PMID 41614769, 2025). "In AGS gastric cancer cells, we observed consistent 1.3-8-fold up-regulation of pro-apoptotic genes such as BAD, BAX, BID, and FAS after control lettuce and lettuce fortified with organic iodine, as compared to negative control." (PMID 36296971, 2022). "Further mechanism study has revealed that SNHG5 down-regulates BAX expression and up-regulates BCL-2 expression, thereby inhibiting apoptosis and promoting DDP resistance of gastric cancer cells." (PMID 32460771, 2020). "Knockdown of PLOD2 downregulated the expression of BCRP protein, while increasing BAX and decreasing the level of BCL2 promoted apoptosis, reducing the resistance of gastric cancer to 5-FU." (PMID 32284742, 2020). "The interference with HOTAIR can decrease the expression of Wnt and β-catenin, thereby increasing the BAX/BCL-2 ratio, activating caspase-3, promoting apoptosis, and reversing DDP resistance in gastric cancer cells in vitro and in vivo." (PMID 32460771, 2020). "In a Chinese study, Nox4 expression was correlated with tumor size and poor prognosis in 90 patients with gastric cancer and knockdown of NOX4 expression blocked cell proliferation and the expression of Cyclin D1, BAX and so on in vitro." (PMID 30513726, 2018). "Contrarily, BAX gene mRNA expression levels do not exhibit a direct correlation with the incidence of either gastric cancer or peptic ulcer disease." (PMID 41614769, 2025). "However, in the case of gastric cancer, in silico studies using the TIMER database showed a positive correlation between NFKB2 and BAX gene expression (r = 0.341; p < 0.001)." (PMID 41614769, 2025). "Mechanisms underlying this resistance involve the overexpression of Cell Retinoic Acid Binding Protein 2 (CRABP2), which promotes the binding of BAX and PARKIN in gastric cancer cells, thereby facilitating ubiquitin-mediated BAX degradation and weakening of mitochondrial apoptosis." (PMID 38370477, 2024). "In addition, we also detected expression levels of multiple apoptotic proteins (BAX, BAK and BCL-2) in gastric cancer xenografts, which indicated the pro-apoptotic of LINC00240." (PMID 37072811, 2023).
gastric cancer (continued). "The induction of apoptosis is related to BAX overexpression, BCL-2 downregulation, and inhibition of inflammation, as revealed by the downregulation of IL-6, TNF-α, IL-1β, and IL-8 which modulate cell growth proteins in gastric cancer cells." (PMID 36359261, 2022). "In gastric cancer (GC), SIRT1 silencing or inhibiting its activity by EX527 enhances expression of FOXO1, pro-apoptotic BAX, and E-cadherin, whereas the expression of Ki67, Cyclin D1, anti-apoptotic Bcl-2, Vimentin, MMP-2 and MMP-9 are downregulated, suggesting SIRT1 involvement in GC progression." (PMID 34769241, 2021). "HOTAIR has further been found to target miR-34a and activate the PI3K/AKT pathway, consequently decreasing the expression of caspase-3 and BAX, increasing the expression of BCL-2, inhibiting apoptosis, and inducing DDP resistance in gastric cancer cells in vitro and in vivo." (PMID 32460771, 2020). "Similarly in gastric cancer cells, KD of Rab31 by siRNA reduced expression of the BCL-2, Hedgehog (Hh) signaling transcript GLI1 while increasing BAX protein levels." (PMID 31973201, 2020). "Overexpression of the BAX gene had a negative effect on cell growth in human gastric cancer, owing to the induction of apoptosis and to the enhancement of cell chemosensitivity." (PMID 23311997, 2013). "Thus, it is possible that BAX gene expression is not directly related to the development of peptic ulcer disease or gastric cancer." (PMID 41614769, 2025). "BAX gene was not altered in any of the analyzed gastric cancer sample." (PMID 40652278, 2025). "Moreover, RAD51 and BAX also exhibited negative correlations (Cor = -0.04, FDR = 0.41 for RAD51 and Cor = -0.09, FDR = 0.074 for BAX) with expression in gastric cancer." (PMID 40652278, 2025).